KLF4 (KLF transcription factor 4)
Diseases named in the same sentence as KLF4 in open-access papers (continued):
Sharing a sentence is not in itself a finding about the gene and the disease.
tumor (continued). "The overexpression of KLF4 leads to the inhibition of tumor growth, cell proliferation and angiogenesis in vitro and in tumor xenografts, confirming its tumor suppressive role." (PMID 39135777, 2024). "To test if disruption of Klf4 expression affects BLM tumor differentiation, we simulated Klf4 knockout (KO)." (PMID 38893159, 2024). "While on the basis of knocking down MACC1 and continuing to knock down KLF4, the diameter of tumor cell microspheres in the shKLF4-shMACC1 group was significantly enlarged, and the number of spheres was also partially restored." (PMID 39695175, 2024). "In the present manuscript, the main mechanisms of epigenetic modulation of KLF4 expression in tumor cells are described and commented." (PMID 39135777, 2024). "There is emerging evidence indicating that Krüppel-like factor 4 (KLF4), a potent tumor repressor, regulates the transition of VSMCs into osteogenic phenotypes in both murine and humans." (PMID 38700707, 2024). "At present, there is still little research on the tumor inhibitory effect of Klf4, and more results are needed to support this finding." (PMID 38699229, 2024). "KLF4 functions as a tumor suppressor and its transcriptional activity is repressed by the binding of STAT5A to its promoter." (PMID 38879589, 2024). "Studies over the past three decades have shown that KLF4 inhibits tumor progression in most types of tumors." (PMID 37031197, 2023). "For instance, in vivo models of colonic carcinogenesis revealed the tumor suppressive function of KLF4, which is typically down-regulated in colorectal cancer." (PMID 37176108, 2023). "Collectively, KLF4 plays significant multifaceted roles in tumor cells, immune cells infiltrating tumors, and their crosstalk." (PMID 36936440, 2023). "KLF4 also inhibited PDA cell EMT by downregulating Caveolin-1, which was closely associated with tumor metastasis." (PMID 37031197, 2023). "KLF2 and KLF4 possess anti-inflammatory effects but also impact macrophage proliferation, differentiation, activation, and tumor growth inhibition, demonstrating their dual nature in tumor immunity." (PMID 37533434, 2023). "Compared to normal tissues, the pan-cancer data analysis found that KLF4 expression was low in tumor tissues." (PMID 36936440, 2023). "In this sense, it has been previously shown that constitutive upregulation of c-MYC and KLF4, as seen in TNF-α + E1 exposed HeLa cells, is associated with CSC enrichment and tumour aggressiveness." (PMID 36674737, 2023). "The significant tumor suppressive effect of KLF4 and its prognostic value highlighted future application of KLF4 as a therapeutic target or response biomarker in HCC." (PMID 36936440, 2023). "KLF4 also inhibits tumor development by regulating metabolism-related molecules, including LDHA and suppressing aerobic glycolysis pathways." (PMID 37031197, 2023). "In colon cells, CDX2 upregulated KLF4 by binding to KLF4 promoter and reducing the association of histone 3 lysine 4 trimethylation with KDM5B demethylase, and acting as a tumor suppressor." (PMID 37031197, 2023). "Nevertheless, tumor suppression is insufficient to recapitulate its function, and the precise molecular basis for KLF4 function in the tumor remains obscure." (PMID 36936440, 2023). "KLF4 was found to also act as an oncogene to promote carcinogenesis by affecting CSC stemness maintenance and CSC-associated tumor metastasis." (PMID 37853437, 2023).
tumor (continued). "KLF4, a vital regulator of the NOTCH pathway, promotes ineffective angiogenesis in tumors via the NOTCH pathway, leading to hypoxia and diminished tumor growth, and KLF4 also inhibits NOTCH-1 in combination with SP3 transcription." (PMID 36761967, 2023). "We developed two nomograms that incorporate KLF4 expression, tumor differentiation, and TNM stage to establish more accurate prognostic models for OS and RFS in HCC patients." (PMID 36936440, 2023). "KLF4 also plays a positive role in inhibiting tumor proliferation, epithelial-to-mesenchymal transition (EMT), and metastasis." (PMID 37031197, 2023). "Given its complex role in tumor biology, it is difficult to universally define KLF4 as a therapeutic target for all types of tumors." (PMID 37031197, 2023). "TRAF7, an e3-ubiquitin ligase on the TNF-α/NF-κB pathway, can interact with the N-terminus of KLF4 protein to degrade it via ubiquitin, thereby eliminate the tumor-suppressor effect of KLF4 and enable cancer cell migration and invasion in vitro and vivo." (PMID 36761967, 2023). "It has been reported that exosomal miR-25-3p from CRC cells promotes vascular leakiness, vascular permeability, and angiogenesis via targeting KLF2 and KLF4 to enhance tumor metastasis." (PMID 36793126, 2023). "KLF4 (a well-established tumor suppressor in the gut) is induced by IFNγ in the HT-29 cell line, where it inhibits proliferation and induces apoptosis." (PMID 38067370, 2023). "With this notion in mind, more detailed analysis was needed to explore how KLF4 affected tumor immunity in HCC." (PMID 36936440, 2023). "Other study found that KLF4 inhibited the proliferation and invasion of tumor cells and suppressed the progression of ESCC." (PMID 37031197, 2023). "This operation restricts the glycolysis-dependent altered metabolic reprogramming of cancer cells, suggesting a potential tumor-suppressive function for KLF4 in this context." (PMID 37835497, 2023). "In cancer, KLF4 can have a dual role according to the type of cancer or tumor stage, acting either as a tumor suppressor or oncogene." (PMID 37004094, 2023). "KLF4 acts as a context-dependent antitumor or tumor-promoting factor, holding limited potential as a therapeutic target." (PMID 37031197, 2023). "Tumor subtypes clearly dictate the regulatory roles for KLF4 as exemplified by the evidence that KLF4 is more likely to promote tumor development from endothelial and squamous cells, while the opposite role in others." (PMID 37031197, 2023). "The interaction between KLF4 and this signaling pathway has become the target of multiple microRNAs involved in tumor regulation." (PMID 36761967, 2023). "Given that KLF4 stability as a tumor suppressor depends on the interaction of m6A methylation reader protein IGF2BP2 with two unique m6A methylation sites in the KLF4 transcript." (PMID 37345019, 2023). "Nomograms constructed using KLF4 expression, tumor differentiation, and TNM stage provided a more accurate prognostic assessment of HCC patients than TNM stage alone." (PMID 36936440, 2023). "Some scholars believe that the function of KLF4 as an oncogene or tumour suppressor is modulated by its complex interactions with several tumour microenvironments." (PMID 37559082, 2023). "Currently, a few compounds have been designed to target the tumor-regulating effects of KLF4, and are available for clinical trials." (PMID 37031197, 2023). "The GSVA program explored the link between KLF4 expression and tumor-infiltrating immune cells, and CAMOIP was used to construct KLF4 expression immune scores." (PMID 36936440, 2023). "The level of KLF4 (p < 0.05), tumor differentiation (p < 0.001), and TNM stage (p < 0.001) were independently associated with OS and RFS in our cohort, as determined by cox regression." (PMID 36936440, 2023). "KLF4 disturbs tumor angiogenesis by mediating the expression of members of NOTCH and the vascular endothelial growth factor (VEGF) signaling pathways." (PMID 36761967, 2023).
tumor (continued). "The re-expression or abnormal dysregulated expression level of stemness genes, like oct4, sox2, klf4 and klf5, in differentiated cells are a common feature of the tumorigenesis process and have been well documented in many tumor types." (PMID 38137514, 2023). "For example, KLF4 is a tumor suppressor; however, it becomes indispensable as a proliferative factor during intestinal epithelium regeneration following radiation injury." (PMID 37173904, 2023). "According to the cellular originand type of cancer, KLF4 can exhibit either tumor suppressor or oncogenicproperties." (PMID 37636966, 2023). "KLF4 also inhibits the tumor proliferation and metastasis of non-small cell lung cancer (NSCLC) through downregulating cyclin D1, upregulating p21, and inhibiting MSI2: an activator of the JAK/STAT3 signaling pathway that promotes metastasis." (PMID 37760529, 2023). "Following on from this idea, the downregulation of alpha-aminoadipic acid (RM = 0.01) is also related to tumor shrinkage through the activation of a tumor suppressor known as KLF4." (PMID 37570523, 2023). "In tumor tissues, KLF4 showed elevated expression levels in cell lines enriched with CSCs and maintained self-renewal of CSCs by targeting dual-specificity tyrosine-(Y)-phosphorylation-regulated kinase 2 (DYRK2) and inducing telomerase expression." (PMID 36761967, 2023). "We observed a marked decrease in KLF4 regulon activity in HPV-positive tumours compared with in HPV-negative tumours in this study, which was further validated in the TCGA-HNSCC cohort." (PMID 37914932, 2023). "A small molecule named APTO-253, an inducer of KLF4, has been approved to have anti-tumor activity against cancer cells and in animal models through KLF4 upregulation." (PMID 36936440, 2023). "IHC staining for SALL4, LIN28A, and KLF4 was predominantly observed in the epithelial cells of the tumour islands." (PMID 37559082, 2023). "Studies have demonstrated that KLF4 performs a tumor suppression function in gastrointestinal cancers, T-cell acute lymphoblastic leukemia (T-ALL), lung cancer, meningioma and bladder cancer." (PMID 37853437, 2023). "It is known that KLF4 can regulate tumorigenesis and this role can be further complicated by tumor types and stages." (PMID 37031197, 2023). "Tumor development involves a dedifferentiation process which occurs with ectopic re-expression of stemness genes like Octamer-4 (Oct4), Nanog, Kruppel-like factor 4 (Klf4) or Kruppel-like factor 5 (Klf5)." (PMID 38137514, 2023). "On the other hand, in KIRP, CDK1, CDK4, HIPK2 and MYC expression increased with the pathological and clinical stage of the tumor, whereas KLF4 decreased." (PMID 37047552, 2023). "The objective of this study is to assess the role of KLF4 as a potential biomarker for the prognostic prediction of HCC after resection and its association with tumor immune infiltrates." (PMID 36936440, 2023). "KLF4 also inhibited the migration and invasion of tumor cells by suppressing biological enzymes, including TIMP-1 and TIMP-2." (PMID 37031197, 2023). "The bidirectional regulation of tumorigenesis is also an aspect that distinguishes KLF4 from most KLFs, probably due to the different activities of the KLF4 transcriptional repression or activation domains in different tumor types/subtypes." (PMID 37031197, 2023). "NOTCH inhibitors, such as dibenzoazepine, and gamma-secretase inhibitors demonstrate anti-tumor activity and have been shown to induce expression of KLF4." (PMID 37173904, 2023). "Given its role as a tumor suppressor, induction of KLF4 represents a potential pathway to CRC treatment." (PMID 37173904, 2023). "Activated by KLF4, the TGF-β pathway can relieve KLF4 suppression by inhibiting miR-7-5p and jointly promote tumor cells to escape from cytotoxic T lymphocyte-mediated lysis." (PMID 36761967, 2023).
tumor (continued). "KLF4 acts as an oncogene or tumor suppressor depending on the types of cancer, indicating the necessity of a better understanding of its cellular context in HCC." (PMID 35383144, 2022). "Kruppel-like factor 4 (KLF4) is a zinc finger transcription factor that plays as a tumor suppressive gene in CRC." (PMID 36333703, 2022). "Here, we employed a counterintuitive approach of overexpressing Yamanaka factors (Oct4, c-Myc, Sox2, and Klf4) and examined a conditioned medium (CM)-based treatment option with induced tumor-suppressing cells (iTSCs)." (PMID 35547745, 2022). "These functional investigations suggest that decreased expression of KLF4 promoted tumour progression and poor prognosis." (PMID 35177016, 2022). "The upregulation of KLF4 distinctly relieved the HADHB knockdown-induced tumour promoting effects on cell viability (P < 0.05 or P < 0.01), invasion, and migration (both P < 0.05)." (PMID 36518312, 2022). "However, the molecular mechanism of this tumor-specific KLF4 mutation is unknown." (PMID 35996584, 2022). "A significant reduction in tumour volumes, however, was evident in the KLF4-KO group compared to control animals (p < 0.05)." (PMID 35359423, 2022). "KLF4 is frequently decreased or lost in epithelial cancers, attributing it a role as tumor suppressor." (PMID 35063803, 2022). "Overexpression of KLF4 also weakened the inhibitory effects of sh-CHRM3-AS2 on tumour weight and volume (P < 0.01)." (PMID 35359381, 2022). "In the relationship that links EMT and tumor angiogenesis, the Twist1-Jagged1-kruppel-like factor 4 (KLF4) axis appears to play a crucial role." (PMID 35873564, 2022). "For example, KLF4 has multiple functions and can be either a tumor suppressor gene or a proto-oncogene in tumors." (PMID 35093082, 2022). "Previous studies indicated that the genetic context plays a decisive role in switching KLF4 between a tumour suppressor and a tumour promoter." (PMID 36539799, 2022). "In those conditions, mRNA expression of CSC (Cd133, Epcam and Aldh), of pluripotency (Klf4) and of tumor cell (Gpc3 and Afp) markers were found significantly induced by IL-17 when compared to those from control non-treated LPCs." (PMID 35342340, 2022). "Due to the direct interaction between SOX2/NANOG/BMI1/KLF4 in the invasiveness of tumor cells, as well as its biological significance in the progression of ESCC, SOX2 expression can enhance malignancy by inducing stemness properties and EMT in ESCC." (PMID 36553636, 2022). "In conclusion, this study revealed a positive DUB3/KLF4 feedback loop that inhibits tumor growth and chemoresistance in HCC." (PMID 35383144, 2022). "Knockdown of DUB3 and KLF4 was performed to examine the role and underlying mechanism of DUB3 in cell proliferation, chemoresistance, and xenograft tumor growth in HCC." (PMID 35383144, 2022). "KLF4 serves as a tumor suppressor by turning glucose metabolism into less Warburg-like, but its levels are frequently decreased in colorectal tumors." (PMID 36077352, 2022). "The data revealed that the proportion of Slug-positive cells was significantly higher in recurrence/second tumor samples (p = 0.007), whereas KLF4 was present at the same level in primary and progressed HNSCC (recurrence or second tumor)." (PMID 36289744, 2022). "Knockdown of MEX3A with siRNA or addition of KLF4 agonist significantly suppressed tumor growth both by increasing differentiation status of cancer cells and by suppressing their proliferation." (PMID 36276637, 2022). "Nanog, octamer-binding protein 4 (OCT4), SRY-box 2 (SOX2) and Kruppel-like factor 4 (KLF4) are key participants of tumor stemness." (PMID 35864972, 2022).
tumor (continued). "The zinc finger protein Krüppel-like factor 4 (KLF4) is responsible for regulating gene transcription and cell fate, promoting malignant transformation, cell differentiation, tumor suppression, and stem cell properties." (PMID 35445029, 2022). "KLF4 functions both as a tumor suppressor and an oncogene, which is involved in cell differentiation and cell-cycle arrest." (PMID 35154316, 2022). "KLF4, as an anti-proliferative factor in differentiated epithelia, play a dual function depending on tumor type, tissue, and cancer stage." (PMID 36553636, 2022). "The anti-tumour effect of CHRM3-AS2 silencing was weakened by miR-370-5p silencing or KLF4 overexpression." (PMID 35359381, 2022). "We have previously demonstrated that KLF4 acts as a tumor suppressor in HCC by upregulating the MET pathway." (PMID 35383144, 2022). "KLF4 overexpression was verified to result in the inhibition of tumour cell migration and invasion by reducing the levels of metastasis-related MMP2, MMP9, and N-cadherin." (PMID 36518312, 2022). "miR-7 has been described as a tumor suppressor capable of annulling the stemness of prostate cancer cells, inhibiting tumorigenesis by suppressing KLF4." (PMID 36012357, 2022). "IFITM3 expression is reduced by Krüppel-like factor 4 (KLF4), a known tumor suppressor that interacts with β-catenin and thus inhibits Wnt/β-catenin signaling in the human intestinal epithelium." (PMID 36466909, 2022). "KLF4 has been characterized as having tumor-suppressing activities in many cancers, including gastric, colorectal, liver, and pancreatic cancer as illustrated herein." (PMID 36077352, 2022). "In vivo, suppression of the anti-inflammatory BDM phenotype, specifically, via myeloid knock out of Krüppel-like Factor 4 (KLF4) significantly reduced EO771 tumour growth in the brains of C57BL/6 mice." (PMID 35359423, 2022). "In a further step, we examined the HPV-product stabilization effect of KLF4 at protein level in paraffin embedded tumor tissue samples and three HNSCC cell lines." (PMID 35219646, 2022). "The results showed that the expression of Ki67 was down-regulated by CHRM3-AS2 silencing in tumour xenografts, and this inhibitory effect was weakened by KLF4 overexpression." (PMID 35359381, 2022). "Compared with the control, knockdown of DUB3 and KLF4 alone or in combination markedly promoted tumor growth and resulted in remarkably increased tumor volumes and tumor weights in mice at four weeks after tumor cell implantation." (PMID 35383144, 2022). "We found that the promoting effects of LINC00629 on tumour development and lung metastasis were abolished by KLF4 or LAMA4 depletion in nude mice." (PMID 36539799, 2022). "In contrast to Slug, which is related with EMT and therapy resistance, experimental overexpression of KLF4 induced a re-epithelialization of EMT tumor cells." (PMID 36289744, 2022). "Many studies have confirmed that KLF4 is a transcription factor related to tumor molecular regulatory mechanism, and we had also confirmed that its differential expression can affect malignant behaviors of cancer cells." (PMID 35027543, 2022). "Next, to determine the effect of anti-inflammatory BDM, specifically, on tumour growth, myeloid specific deletion of KLF4 was used to suppress STAT6-mediated anti-inflammatory macrophage activation." (PMID 35359423, 2022). "When miR-92a is overexpressed in CRCs, it targets KLF4 and downstream p21, promoting tumour growth and invasion." (PMID 36776356, 2022). "Yang and Zheng identified the tumor suppressor role of KLF4 in CC and found that promoter hypermethylation of KLF4 can inactive its tumor suppressor function in CC." (PMID 35154316, 2022). "The upregulation of KLF4 also notably abolished the HADHB knockdown-induced tumour promoting effects on cell viability, migration, and invasion." (PMID 36518312, 2022).